LEP (leptin)
Diseases named in the same sentence as LEP in open-access papers (continued):
Sharing a sentence is not in itself a finding about the gene and the disease.
Insulin resistance (continued). "LVM correlates with circulating leptin levels, and with insulin resistance, and decreases of LVM and of leptin levels are correlated in obese normotensive subjects." (PMID 19619292, 2009). "Insulin resistance, increased leptin and NEFA levels have been indicated to be possible factors augmenting sympathetic nervous activation in the metabolic syndrome." (PMID 18416854, 2008). "Insulin resistance was positively correlated with body trunk fat, BMI, body fat mass (kg), leptin and body fat percentage." (PMID 18553029, 2008). "Future studies are needed to clarify the relevance of inflammation dependent leptin secretion for insulin resistance." (PMID 19087258, 2008). "Inflammation caused by cardiac surgery increased insulin resistance in a time dependent manner which was paralleled by an induction of cortisol, TNFα, IL6, resistin and leptin while adiponectin serum levels were decreased." (PMID 19087258, 2008). "Insulin resistance was positively correlated with body trunk fat (r = 0.457; p = 0.001), BMI (r = 0.417; p = 0.003), body fat mass (kg) (r = 0.386; p = 0.006), leptin (r = 0.307; p = 0.045) and body fat percentage (r = 0.285; p = 0.047)." (PMID 18553029, 2008). "Nevertheless, the relationship between leptin and insulin resistance in patients with chronic viral hepatitis (CVH) seems obscure at present; both presence and absence of association between serum leptin and insulin levels have been observed in CVH patients." (PMID 17540037, 2007). "Several studies have been conducted in India which have shown relationships between insulin resistance, body composition, lipoproteins, leptin and adiponectin; yet for our purposes, only papers with data from Asian Indian immigrants will be discussed." (PMID 16606459, 2006). "Our unpublished study showed that high fat diet resulted in insulin resistance and higher serum leptin level in rats." (PMID 15491498, 2004). "As the process progresses, inefficient leptin action can lead to the opposite of leptin's protective effects, e.g., hyperphagia, decreased fat oxidation, increased tissue TG levels, insulin resistance, and overweight." (PMID 15530168, 2004). "Insulin resistance in the HHTg strain may be due to elevated leptin and NEFA levels, as well as decreased GLUT4 in skeletal muscle." (PMID 42058781, 2026). "A chronic excess body weight condition increases production of free fatty acids, cytokines such as TNF-α and IL-6, and leptin from adipose tissue, whereas it decreases adiponectin production, which together lead to the development of insulin resistance and chronic hyperinsulinemia." (PMID 41376649, 2026). "Observational studies demonstrated inverse associations between serum 25(OH)D levels and insulin resistance, body mass index (BMI), and leptin, but not with total testosterone." (PMID 41901143, 2026). "The endocrine function of AT in relation to insulin resistance—particularly through adipocytokines such as adiponectin and leptin, along with various interleukins and nitric oxide (NO) alterations—may drive megakaryocytes to produce larger platelets." (PMID 39388707, 2025). "However, after 8 weeks of treatment with stevia, garlic, and aerobic exercise, the stevia group exhibited the most significant changes in leptin and ghrelin receptor mRNA expression, glucose levels, and insulin resistance." (PMID 40087612, 2025). "Studies have shown that aldosterone treatment of cultured adipocytes increases the expression of interleukin-6 (IL-6), plasminogen activator inhibitor-1, chemerin, and leptin, which are key players in the inflammatory cascade that can lead to insulin resistance." (PMID 39996060, 2025). "Moreover, leptin improves metabolic abnormalities, including insulin resistance and hyperlipidemia, when administrated to lipoatrophic mice which have low levels of leptin due to the lack of subcutaneous adipose tissue." (PMID 40635334, 2025).
Insulin resistance (continued). "Leptin is associated with maternal obesity and pre-pregnancy body mass index (BMI), but placental production of leptin is notably increased in women with GDM, contributing to hyperleptinemia and maternal insulin resistance as well as fetal macrosomia." (PMID 40235646, 2025). "In fact, blocking compensatory leptin response to insulin resistance by inhibiting its synthesis or its effector actions has been implied to be a potential mean to improve metabolic phenotype imposed by insulin resistance." (PMID 40066865, 2025). "Leptin, through the glucose-stimulated insulin secretion pathway, is directly related to the secretion of insulin granules, which may promote insulin resistance." (PMID 41347218, 2025). "Furthermore, the observed positive correlations between LEP, BioLEP, and fasting insulin levels reinforce the role of leptin as a marker of insulin resistance in pediatric obesity, a relationship well documented in the literature." (PMID 40586327, 2025). "Thus, peripheral insulin resistance and hyperinsulinemia can lead to alterations of CNS leptin signaling centrally to foment continued weight gain." (PMID 40950761, 2025). "Elevated plasma glucose also correlated significantly with markers of insulin resistance and metabolic syndrome risk, including HOMA-IR (r = 0.39, p = 0.01), triglyceride/HDL cholesterol ratio (r = 0.33, p = 0.04) and leptin/adiponectin ratio (r = 0.37, p = 0.02)." (PMID 41455970, 2025). "However, both groups of women displayed a similarly large increase in insulin resistance and alterations in levels of adipokines, such as increased leptin and soluble leptin receptor (LepR)." (PMID 41202005, 2025). "In animal models, SYR could lower body weight and fat mass, lower leptin levels, enhance adiponectin circulation, and improve insulin resistance." (PMID 41170185, 2025). "The physiological mechanisms linking adiposity to high blood pressure could be increased leptin production, insulin resistance, and the release of inflammatory markers." (PMID 41357017, 2025). "Therefore, improving leptin and insulin resistance is considered an important strategy for the treatment of MAFLD in clinical practice." (PMID 40337517, 2025). "Insulin resistance may impair signaling pathways that regulate apelin receptor expression and leptin secretion." (PMID 41302116, 2025). "Conversely, decreased insulin resistance, as observed in the stevia-fed group, may contribute to enhanced leptin sensitivity, allowing for more effective regulation of hunger and satiety cues." (PMID 40087612, 2025). "In the C200 group, both serum insulin and leptin levels were significantly reduced compared with those of the Veh group, suggesting that the improvement in insulin resistance by CJE may be from the regulation of energy balance." (PMID 39815341, 2025). "Behavioral mechanisms may also be involved while triglyceride has been reported to induce central leptin and insulin resistance." (PMID 40281857, 2025). "For instance, insulin resistance might alter leptin signaling within a hypothalamic cell line, and leptin resistance could lead to the suppression of insulin signaling." (PMID 40283443, 2025). "However, as pregnancy progresses, a surge in maternal and placental hormones, including oestrogen, progesterone, leptin, cortisol, placental lactogen, and placental growth hormone collectively promote a state of insulin resistance." (PMID 39841354, 2025). "Additionally, a reduction in cord plasma adiponectin levels was observed in the GDM newborns, while the elevated leptin/adiponectin ratio showed a positive correlation with fetal insulin resistance." (PMID 40003257, 2025). "Elevated leptin, under insulin resistance and hyperinsulinaemia, further reinforces this oncogenic landscape by activating mitogenic, anti-apoptotic, and pro-angiogenic pathways (JAK2-STAT3 and PI3K-Akt) and maintaining cancer stem-like phenotypes in many tumour types." (PMID 41586225, 2025).
Insulin resistance (continued). "On the other hand, leptin displayed a contrasting pattern in which high levels were observed in individuals with insulin resistance or low HDL (p < 0.001), while subjects with high blood pressure and abnormal levels of triglycerides and had the lowest levels of this adipokine." (PMID 39940942, 2025). "Integrating biomarkers—such as high-sensitivity C-reactive protein (hs-CRP), adiponectin, leptin, and insulin resistance markers—could help elucidate the biological pathways linking BRI to mortality and potentially identify novel therapeutic targets." (PMID 41561124, 2025). "For example, leptin, the main mediator of the control of appetite and energy balance, signals the brain about the body's energy stores, whereas adiponectin protects against insulin resistance and has remarkable anti-inflammatory properties." (PMID 40013194, 2025). "Although nicotine’s appetite-suppressing effects may help current smokers maintain body weight, former smokers often experience increased leptin levels and weight gain after quitting, potentially exacerbating insulin resistance." (PMID 41296790, 2025). "A 2023 study of 575 NAFLD patients found that the adiponectin–leptin ratio (ALR) could predict disease severity independently of insulin resistance." (PMID 40725208, 2025). "While other research on the relationship between leptin and metabolic syndrome in Mexican-Americans is limited, some studies suggest a negative association with insulin resistance, consistent with findings in European and Middle Eastern populations." (PMID 40362681, 2025). "These factors can lead to the observed decrease in apelin receptor mRNA expression and leptin concentration, which may predict the outcome of insulin resistance and poor glucose metabolism before the manifestation of GDM." (PMID 41302116, 2025). "Methods: uPTM3-FetA levels in aliquots of 24 h urine specimens, routine laboratory renal, metabolic and inflammatory tests, adipokines (leptin, adiponectin, resistin), and insulin resistance, assessed as the estimated glucose disposal rate (eGDR), were measured in a cohort of 169 adult T1D patients." (PMID 40002573, 2025). "Moreover, the relationship between leptin and insulin resistance warrants further exploration to clarify their roles in the pathophysiology of youth-onset diabetes." (PMID 40630340, 2025). "And the possible mechanisms were inflammation, insulin resistance, hormone, and leptin." (PMID 41245415, 2025). "Adipokine imbalance has also been proposed as a contributing factor: elevated leptin and insulin resistance may promote Th1/Th17 polarization and oxidative stress, mechanisms that have been correlated with biomass-associated COPD." (PMID 40722673, 2025). "Adipokine signaling networks—especially leptin, adiponectin, chemerin, and visfatin—emerged in concert with basic pathophysiological processes, including insulin resistance, fibrosis, and bariatric surgery as a therapeutic intervention during the middle period (2013–2017)." (PMID 40868109, 2025). "Inhibiting SOCS3 to ameliorate immune homeostasis, inflammation, and metabolic issues, such as leptin and insulin resistance, might be a promising therapeutic approach." (PMID 40104138, 2025). "The notion that reducing leptin in DIO animals improves metabolic function might seem at odds with the finding that the in chow-fed ob/+ heterozygous mice display reduced leptin concentrations, resulting in increased adiposity and mild insulin resistance." (PMID 40393800, 2025). "After adjusting for BMI, waist circumference, homeostatic model assessment for insulin resistance (HOMA-IR), hypertension, lipid levels, and APOE ε4 status, individuals in the highest sex-specific tertile of leptin had a lower risk of developing dementia and AD." (PMID 41516046, 2025). "They suggested that adults with NF1 could have low levels of leptin and resistin and high levels of adiponectin which could decrease insulin resistance and increase insulin sensitivity." (PMID 40376359, 2025).
Insulin resistance (continued). "T2DM and insulin resistance are also connected to elevated leptin levels." (PMID 40283443, 2025). "Additionally, insufficient sleep disrupts endocrine and metabolic functions, leading to impaired glucose tolerance, insulin resistance and decreased levels of key hormones such as leptin, testosterone, and melatonin." (PMID 40391016, 2025). "Additionally, TSH levels, in combination with leptin, can indirectly lead to insulin resistance by stimulating the synthesis of pro-inflammatory cytokines in fat cells." (PMID 39539932, 2024). "Leptin levels increase along with fat mass and is up-regulated in adipose tissue from morbidly obese patients; its expression in fat tissue and serum levels correlate with insulin resistance and body mass index." (PMID 38541059, 2024). "Malaria-associated insulin resistance results from interaction of adipokines such as leptin and adiponectin with markers of inflammation and oxidative stress in non-pregnant individuals similar to that observed for pregnancy-related insulin resistance." (PMID 38745311, 2024). "In probiotic group, insulin resistance, HbA1c, glucagon, leptin, and oxidative stress decreased." (PMID 39125375, 2024). "Psoriasis promotes systemic inflammation which, in turn, promotes inflammation in adipose tissue, leading to the release of adipokines (resistin, leptin, and visfatin) and proinflammatory cytokines (IL-6 and TNF-α), which are directly linked to increased insulin resistance." (PMID 38473907, 2024). "While the exact process through which higher body weight causes an increase in BP is not completely understood, previous studies indicate that a combination of insulin resistance, elevated leptin levels, and heightened sympathetic activity are the main culprits in obese individuals." (PMID 38606264, 2024). "Plasma leptin stimulates oxidative stress, inflammation and insulin resistance." (PMID 38672494, 2024). "Furthermore, both insulin resistance and leptin are biologically intertwined with inflammation and oxidative stress." (PMID 38615017, 2024). "High levels of leptin do not always lead to a reduction in food intake, also a study has shown that serum leptin levels in obese adults are higher than in fit controls, indicating resistance to the effects of leptin in these people (similar to insulin resistance in type 2 diabetes)." (PMID 38807723, 2024). "Leptin may have a role in the development of hepatic steatosis by promoting insulin resistance and altering insulin signaling in liver cells, leading to an increased accumulation of fatty acids inside the cells." (PMID 39229578, 2024). "A disorder in this tissue triggers reduced production of adipocytokines, such as adiponectin, and upregulation of the expression of leptin, tumor necrosis factor-α (TNF-α), and interleukin-6 (IL-6), promoting insulin resistance in association with increased visceral adiposity." (PMID 39273464, 2024). "Previous studies have demonstrated that the conditional ablation or impaired function of median eminence tanycytes results in a phenotype similar to that observed in our model, characterized by increased adiposity, insulin resistance, elevated caloric intake, and leptin resistance." (PMID 39047908, 2024). "In subjects with metabolic syndrome, a high content of polyunsaturated fatty acids, tocopherols, and phenolic compounds in the diet led to reduced insulin resistance and glucose levels, improving lipid parameters and modulating the leptin and adiponectin levels in the serum." (PMID 39339791, 2024). "The triglyceride and total cholesterol, which are blood lipid indicators, and the levels of leptin, which is an insulin resistance indicator, were significantly increased in the obese group but were significantly decreased in the fermented blackberries-treated group." (PMID 38892352, 2024). "Additionally, ω-6 can stimulate inflammation, triglyceride synthesis, oxidation, and hormone resistance (leptin and insulin resistance)." (PMID 38399435, 2024).
Insulin resistance (continued). "In addition to TNF-α, IL-6 acts on adipose tissue to increase leptin secretion, suppress satiety, and increase adipose tissue lipolysis, which, in turn, promotes hepatic gluconeogenesis and hepatic insulin resistance." (PMID 39204094, 2024). "Additionally, Lactobacillus relieves pancreatic β-cell dysfunction, which helps ameliorate insulin resistance while decreasing the Bacteroides/Bacteroidetes ratio, which is positively correlated with body weight and LEP levels." (PMID 38999906, 2024). "Moreover, in-vitro and in-vivo studies have shown that LF improves insulin sensitivity even in the presence of existing insulin resistance, reduces weight gain, and regulates blood sugar levels, leptin, and lipid levels in animal models." (PMID 39092264, 2024). "Moreover, the levels of leptin and insulin, which are insulin resistance indicators, significantly increased in the obese group but were significantly decreased in the PGA-K-treated group." (PMID 38542720, 2024). "Leptin has also been shown to be positively associated with atherosclerosis assessed by CAC in a cross-sectional study on 200 participants, aged between 35 and 75 years with T2DM (which is hyperinsulinaemia with hyperglycaemia, with insulin resistance)." (PMID 39062126, 2024). "Visceral adipocytes produce and release a series of adipokines, including interleukin-6, adiponectin, and leptin, which may lead to increased insulin resistance." (PMID 39348367, 2024). "It is postulated that elevated leptin concentrations may contribute to insulin resistance by interfering with insulin signaling pathways." (PMID 39683486, 2024). "Our data also were in line with the study that showed a strong link between mitochondrial dysfunction and the pathology of T2DM that may lead to leptin and insulin resistance." (PMID 39478962, 2024). "Higher serum leptin levels were found in a study of patients with T2D while a lower adiponectin/leptin ratio correlated with higher body mass index (BMI), body fat, waist-to-height ratio, and plasma resistin, indicating potential early insulin resistance in obese adults." (PMID 39457523, 2024). "Additionally, hyperglycaemia and adipokines, such as leptin and resistin, have also been related to the development of insulin resistance in different tissues." (PMID 38473949, 2024). "The short-term effects of rapid weight loss, such as a reduced metabolic rate and alterations to insulin and leptin levels, may prelude the more pronounced metabolic disturbances that occur during weight regain, such as insulin resistance." (PMID 38392975, 2024). "Moreover, we did not further explore the potential role of other markers, such as leptin, insulin resistance, lipids, and visceral adiposity in this mediating effect analysis." (PMID 38455654, 2024). "To examine whether PGA-K is effective against insulin resistance, we determined the levels of leptin and insulin in serum using ELISA." (PMID 38542720, 2024). "On the other hand, T3 may be helpful in increasing leptin and adiponectin levels and in this way reduce insulin resistance." (PMID 38731880, 2024). "Consequently, the leptin/adiponectin ratio was nearly four times higher in males, indicating a heightened insulin resistance in this sex." (PMID 39339665, 2024). "The peripheral actions of leptin consist of the upregulating proinflammatory cytokines such as tumor necrosis factor-α and interleukin-6 (IL-6), mediators that play an important role in the pathogenesis of type 2 DM and insulin resistance." (PMID 38707092, 2024). "Nonetheless, it has been reported that the offspring’s metabolic profile and lipid metabolism can be boosted by inositol, resveratrol, and exercise in the mother, with an improvement in leptin, triglycerides, adiponectin levels, and a decrease in insulin resistance." (PMID 38785533, 2024).